CX3CL1 (C-X3-C motif chemokine ligand 1)
Diseases named in the same sentence as CX3CL1 in open-access papers (continued):
Sharing a sentence is not in itself a finding about the gene and the disease.
atherosclerosis (continued). "Given the clear role of hypercholesterolemia as a risk factor for atherosclerotic diseases, and the functional role of CX3CL1 in atherosclerosis and plaque rupture, we aimed to determine if CX3CL1 levels varied with cholesterol levels in human subjects without known atherosclerotic disease." (PMID 24995121, 2014). "Its ligand CX3CL1, a membrane-bound chemokine, is increased in atherosclerosis." (PMID 24816562, 2014). "The example of GM-CSF mediated induction of IL-1β, a known mediator of atherosclerosis, provides an illustration of how CX3CL1 and GM-CSF may have multiple downstream effects to augment atherosclerosis." (PMID 24995121, 2014). "Future studies will examine the relationship between CX3CL1 levels and atherosclerotic disease events, and assess whether targeting CX3CL1 levels would represent an effective means to reduce atherosclerosis disease events." (PMID 24995121, 2014). "However, inhibition of H2S formation by PAG increased aortic CX3CR1 and CX3CL1 expression and exacerbated the extent of atherosclerosis." (PMID 22815945, 2012). "Therefore, the present study aimed to investigate the potential role of H2S in atherosclerosis and the underlying mechanism with respect to chemokines (CCL2, CCL5 and CX3CL1) and chemokine receptors (CCR2, CCR5, and CX3CR1) in macrophages." (PMID 22815945, 2012). "Therefore, IR and the CX3CL1/CX3CR1 axis could be two important mechanisms driving accelerated atherosclerosis in these subjects." (PMID 41153665, 2025). "Increased adhesion of activated ECs to platelet in vitro and unscathed human arteries in a CX3CL1‐dependent manner propose that expression of CX3CL1 via ECs, accompanied by von Willebrand factor, is in concern with the development of vasculopathy‐like atherosclerosis." (PMID 39392260, 2024). "Thus, CX3CL1 may play a prominent role in intimal hyperplasia promoting atherosclerosis through increased VSMC proliferation and monocyte trafficking." (PMID 35600479, 2022). "Thus CX3CL1-Fc could be a potent therapeutic option interfering with vascular remodeling and atherosclerosis." (PMID 35600479, 2022). "STAT3 positively regulates the expression of CX3CL1, and then down-regulates the inhibition of CX3CL1 by over-expression of miR-15a-5p, thus forming an elimination feedback loop to control the proliferation of HUVECs and affect the progression of atherosclerosis." (PMID 33456354, 2021). "Thus, during early stages of vascular inflammation, low shear stress typically seen at atherosclerosis-prone regions promotes the induction of endothelial CX3CL1 and monocytic cell recruitment, whereas physiological shear stress counteracts this inflammatory activation of endothelial cells." (PMID 28522896, 2017). "Fractalkine/CX3CL1 expression has been detected on activated endothelial cells, smooth muscle cells (SMCs), macrophages and platelets, and is involved in the development of numerous inflammatory pathologies including atherosclerosis, rheumatoid arthritis, or graft rejection." (PMID 28234900, 2017). "Fractalkine, also known as CX3CL1, is a chemokine with chemotactic activity for monocytes, T cells, and NK cells, all of which play important roles in the development of numerous inflammatory conditions including arthritis, atherosclerosis, insulin resistance and T2D." (PMID 28396851, 2017). "While the studies presented herein were done in vitro, our findings raise the possibility that CD40-mediated CX3CL1 upregulation in endothelial cells may be relevant in vivo by promoting monocyte recruitment during atherosclerosis or arterial injury-driven neointima formation." (PMID 26710229, 2015). "This resulted in lower expression of NF-κB target genes encoding adhesion molecules (VCAM-1, ICAM-1, E-selectin) and chemokines (CX3CL1, MCP-1, RANTES)––molecules that orchestrate endothelial inflammation and leukocyte recruitment in atherosclerosis." (PMID 40871686, 2025).
atherosclerosis (continued). "CX3CL1/CX3CR1 promotes monocyte recruitment and inflammatory cytokine release in atherosclerosis and contributes to the development of atherosclerosis at various stages, including vascular smooth muscle cell migration and angiogenesis." (PMID 40508161, 2025). "Monocyte chemotactic protein 1 (MCP-1), Fractalkine (CX3CL1), RANTES (CCL5), and eotaxin (CCL11) are involved in the development of atherosclerosis." (PMID 36865551, 2023). "Recently, a few documents reported that interaction between the FKN/CX3CL1 and the CX3CR1 is correlated with the angiogenesis and pathogenesis for the atherosclerosis." (PMID 38239497, 2023). "On the other hand, CX3CL1 orchestrates macrophage-VSMC cross-talk, platelet activation, and aggregation, indicating a possible role in atherosclerosis progression other than initiation." (PMID 36555579, 2022). "Previous studies have revealed that the CX3CL1/CX3CR1 axis is responsible for numerous pathological processes, such as atherosclerosis, atherogenesis, nervous system diseases, vasculitis, abnormal heart function, and cancer development." (PMID 35140706, 2021). "First, we identified increased expression of CX3CL1 and IL-15 in the aortic endothelium of monkeys infected with SIV or SHIV and in carotid arteries and plaques of HIV-uninfected persons with atherosclerosis." (PMID 32976527, 2020). "CCL2/CCR2 and CX3CL1/CX3CR1 contribute significantly to the recruitment and stimulation of monocytes/macrophages during the pathogenesis of atherosclerosis, and are expressed in early and advanced atherosclerotic lesions in humans and mice." (PMID 29641559, 2018). "The ‘M3’ chemokine binding protein inactivates key chemokines involved in atherosclerosis (e.g. CCL2, CCL5 and CX3CL1)." (PMID 28282403, 2017). "The knockout and transgenic studies provide convincing proof that individual chemokine-chemokine receptor signalling pathways are important in atherosclerosis, particularly the CCL2/CCR2, CCL5/CCR5 and CX3CL1/CX3CR1 pathways." (PMID 28282403, 2017). "H2S has been reported to hamper the progression of atherosclerosis in fat-fed ApoE−/− mice and down-regulate CX3CR1 and CX3CL1 expression by modulating PPARγ in macrophages and lesion plaques." (PMID 27136542, 2016). "Both CX3CL1-/- and CX3CR1-/- knockout mice crossed into the apoE-/- model of atherosclerosis showed a significant reduction in macrophage recruitment to the vessel wall and decreased atherosclerotic lesion formation compared to normal animals." (PMID 24995121, 2014). "In conclusion, these data indicate that H2S hampers the progression of atherosclerosis in fat-fed apoE−/− mice and downregulates CX3CR1 and CX3CL1 expression on macrophages and in lesion plaques." (PMID 22815945, 2012). "In contrast, inhibition of endogenous H2S formation upregulated aortic expression of CX3CL1 and CX3CR1, thus exacerbating atherosclerosis in aorta." (PMID 22815945, 2012). "The significance of chemokines (CCL2 [monocyte chemotactic protein-1], CCL5 [RANTES] and CX3CL1 [fractalkine]) and their receptors (CCR2, CCR5 and CX3CR1) in atherosclerosis has been demonstrated in animal models and clinical studies." (PMID 22815945, 2012). "CX3CL1 upregulation has also been observed in macrophage-rich human coronary artery plaques and several studies have demonstrated that genetic deletion of either CX3CL1 or CX3CR1 protects mice against atherosclerosis." (PMID 33503867, 2021). "It has been found that AD patients have increased levels of markers of atherosclerosis including fractalkine/CX3CL1, CCL8, M-CSF, and HGF, as well as increased levels of mediators of atherosclerosis such as E-selectin or PI3/elafin, CCL17, and IL-16, which are proportional to SCORAD." (PMID 34551806, 2021).
atherosclerosis (continued). "While CX3CL1 and CX3CR1 are expressed at low levels in healthy vessels, their expression increases significantly under pathological conditions, and pharmacological inhibition of CX3CR1 (the CX3CR1 antagonist F1) has been reported to reduce atherosclerosis." (PMID 32686027, 2020). "Unlike CC-chemokine inhibitor 35K, the M3 protein is capable of sequestering members from all chemokine classes, specifically key chemokines involved in atherosclerosis progression including CCL2, CCL5 and CX3CL1, while displaying selectivity in its binding to individual members." (PMID 28282403, 2017). "More recently the importance of CX3CL1 and its receptor (CX3CR1) in atherosclerosis has emerged." (PMID 28282403, 2017). "CX3CL1 induces tumor necrosis factor alpha (TNF-α), interferon gamma, and interleukin 1 beta (IL-1β) production in chronic obstructive pulmonary disease, pulmonary hypertension, atherosclerosis, RA, HIV infection, and cancer." (PMID 29268768, 2017). "Such co-expression may produce an acute induction of CX3CL1 by a wide range of proinflammatory factors, including TNF-α, LPS and hyperlipidemia, and may lead to vascular injury and atherosclerosis." (PMID 25959742, 2015). "In addition, during atherosclerosis, recruitment of monocytes to atherosclerotic plaque relies on CCR2, CX3CL1/CX3CR1 and CCR5, showing that multiple receptors can be used to recruit these cells to inflammation sites." (PMID 23554169, 2013). "H2S may prevent the progression of atherosclerosis, along with downregulating macrophage CX3CR1 and CX3CL1 expression by a PPAR-γ and NF-κB dependent mechanism." (PMID 22815945, 2012). "In summary, CX3CL1/CX3CR1 is involved in the progression of atherosclerosis and may be an effective therapeutic target, but no effective therapeutic agents have been developed." (PMID 40508161, 2025). "In the present study, we observed that patients with CAS had significantly elevated serum levels of CX3CL1, CXCL12, CCL19, CCL21, CCL2, and CCL5 compared to control individuals, suggesting that these chemokines are intricately involved in the initiation and progression of atherosclerosis." (PMID 40236901, 2025). "Solid literature evidence supports the contribution of specific monocyte subsets to the process of atherosclerosis, with studies in mice demonstrating the recruitment of non-classical monocytes into the plaque via the chemokine receptor CX3CR1 and its ligand CX3CL1/FKN." (PMID 38247848, 2024). "Thus, we have identified a possible feed-forward model of atherosclerosis in which plaque-infiltrating CX3CR1+ CD8 T cells are exposed to vascular EC-derived IL-15 that induces antigen-independent TNF release, resulting in enhanced release of CX3CL1 and IL-15 from ECs." (PMID 32976527, 2020). "CX3CL1 expression by dysfunctional endothelium and/or smooth muscle could provide a mechanism to attract and bind effector CX3CR1+ CD8 T cells and this may be important in the initiation and progression of atherosclerosis in both PLWH and in HIV-uninfected persons." (PMID 32976527, 2020). "We next measured CX3CL1, IL-15, and CD8 T cells in carotid tissues from HIV-uninfected donors with or without atherosclerosis." (PMID 32976527, 2020).
breast carcinoma (63 papers, 2006 to 2025). "It has also been shown that an increase in CX3CL1 expression in the tumour is linked to improved prognosis of many cancer patients with breast carcinoma, colorectal cancer or lung adenocarcinoma, among other cancers." (PMID 39011040, 2024). "Overexpression of CX3CL1 has previously been linked to metastasis and poor prognosis in breast cancer." (PMID 38055067, 2023). "The IL-8 pathway was reported to be important in cancer and CX3CL1 expression was associated with a poor outcome in breast cancer patients as it promotes breast cancer via transactivation of the epidermal growth factor pathway." (PMID 25521548, 2014). "CX3CL1 gene expression in normal breast epithelium has the potential to indicate patient susceptibility to developing breast cancer as well as risk of specific tumor molecular subtypes." (PMID 23029290, 2012). "Finally, CX3CL1 plasma levels were significantly associated with the development of liver metastases in 155 breast cancer patients." (PMID 40145607, 2025). "Indeed, high levels of CX3CL1 are associated with a more favorable prognosis in patients with gastric adenocarcinoma and breast carcinoma." (PMID 28399860, 2017). "More recent studies have linked CX3CL1 expression with poor outcome in breast cancer patients, although whether high CX3CL1 is linked to macrophage recruitment in human breast cancer samples remains to be determined." (PMID 26884646, 2016). "Understanding whether CX3CL1 contributes to early stages of mammary tumorigenesis is of great importance since CX3CL1 may serve as a potential biomarker for breast cancer risk and overall patient prognosis." (PMID 23029290, 2012). "Furthermore, these data are supported by evidence from previously published breast cancer gene expression data sets in which increased CX3CL1 gene expression was linked to ER- tumors." (PMID 23029290, 2012). "In contrast to CXCL9 or CXCL10, and also in contrast to its role in other carcinomas such as breast cancer, CX3CL1 overexpression was found to represent an independent negative prognostic marker in human HGSOC." (PMID 39862711, 2025). "Among these were the chemokines Cx3cl1, Cxcl16 and Ccl17, which were considered candidate chemotactic factors for breast cancer cells with mesenchymal properties." (PMID 38055067, 2023). "With respect to the seven measured chemokines, CXCL5 and CCL23 were substantially decreased in the group of breast cancer patients, while those of CX3CL1 (fractalkine) and CCL5, were significantly elevated." (PMID 35677046, 2022). "Breast cancer brain metastases exhibit a high level of expression of CX3CL1, which functions as a chemoattractant for macrophages and microglial cells." (PMID 33466236, 2021). "Similar results are observed on breast carcinoma: a high expression of CX3CL1 had a positive correlation with a higher number of stromal CD8+ T and NK cells, and intratumoral DCs on histological specimens." (PMID 33391453, 2021). "In breast carcinoma cells from these mice, CX3CL1 induced cell proliferation by the transactivation of ErbB receptors, which in turn increased the phosphorylation of Erk, activating a pathway that has been linked to carcinogenesis." (PMID 33391453, 2021). "In a murine model of breast cancer, the induction of CX3CL1 seemed to increase the infiltration of CX3CR1+ macrophages into the tumor, as well as the vascularization of the tumor." (PMID 33391453, 2021). "In contrast, a high expression of CX3CL1 was observed to have a positively strong association with a high number of stromal CD8+ T cells, NK cells, and intratumoral DCs in breast cancer." (PMID 35140706, 2021). "In breast cancer studies, CX3CL1 was found to have a possible role in tumor metastasis, and high CX3CL1 expression correlates with good prognosis in breast cancer and can also be used as one of the indications for immunomodulatory therapy." (PMID 34603645, 2021).
breast carcinoma (continued). "For this reason, an increase in CX3CL1 expression in the tumor improves the prognosis for patients with breast carcinoma, colorectal cancer, gastric adenocarcinoma, glioma, lung adenocarcinoma and soft tissue sarcomas." (PMID 32466280, 2020). "This is consistent with our results, where MDA-MB-231 cells cultured with EqMDEC CM underwent cell death through apoptosis and showed downregulation of CX3CL1, ASNS, and LCN2, three genes associated with breast cancer progression." (PMID 33239740, 2020). "In our study, we showed that CX3CL1 is selectively elevated in the serum of breast cancer patients with cerebral metastases." (PMID 32321535, 2020). "CX3CL1 stimulates the proliferation of these cells, as has been shown in breast cancer cells, gastric cancer cells, prostate cancer cells and ovarian carcinomas." (PMID 32466280, 2020). "We detected significantly higher levels of CX3CL1 in the sera of breast cancer patients compared with healthy controls." (PMID 30930117, 2019). "In breast cancer cells, CX3CL1 promotes the EMT by delocalizing E-cadherin, which enhances cancer cell motility." (PMID 31077234, 2019). "Consistently, CX3CL1 levels in protein extracts of xenografts were highest in breast carcinoma SKBR7 and barely detectable in colorectal DLD1 tumours." (PMID 29367702, 2018). "Accordingly, CX3CL1 expression in breast carcinoma specimens was shown to correlate with a good prognosis." (PMID 28791023, 2017). "Together, these observations are consistent with the selection for elevated expression of CCL9 and CX3CL1 in breast cancer cells that are metastatic to the liver." (PMID 25882816, 2015). "Park and colleagues described a positive correlation between CX3CL1 expression in breast carcinoma specimens and the number of stromal T CD8+ lymphocytes, intratumoral DCs, and stromal NK cells." (PMID 25165728, 2014). "Several experimental models have analyzed the influence of the CX3CR1/CX3CL1 axis in the biology of breast cancer and the possible therapeutic targeting of CX3CL1." (PMID 24799766, 2014). "Recent studies of breast cancer tissue samples demonstrated that CX3CL1 expression correlates with increased anti-tumor immune cells, including CD8+ T cells, NK cells and Cd1a+ dendritic cells, which correlated with better patient prognosis." (PMID 23029290, 2012). "For instance, it was shown that exposure to proinflammatory cytokines increased the expression of CX3CR1 on human breast cancer cells thereby enhancing migration of these cells toward CX3CL1." (PMID 23029290, 2012). "In conclusion, these study findings indicate a novel mechanism by which FGFR activation in mammary tumor cells promotes macrophage recruitment via induction of CX3CL1." (PMID 23029290, 2012). "For example, in a study of breast cancer, the high expression of CX3CL1 might recruit immune cells, such as CD8+ T cells and NK cells, to exert anti-tumor activity." (PMID 34671562, 2021). "Additionally, CX3CL1 triggered cell proliferation by inducing ErbB receptors through the proteolytic shedding of an ErbB ligand, and these findings support the conclusion that CX3CL1 acts as a positive modifier of breast cancer in concert with ErbB receptors." (PMID 34671562, 2021). "There seems to be important differences in CX3CL1 expression in several breast cancer cell lines." (PMID 33391453, 2021). "Furthermore, adverse features in breast cancers, including lymph node involvement, α-β crystalline expression and high Ki67, were positively correlated with the expression of CX3CL1." (PMID 34671562, 2021). "However, CX3CL1 has also been shown to promote angiogenesis through the recruitment of CX3CR1-expressing macrophages that secrete angiogenic factors in murine breast cancer, hepatocellular carcinoma, lung cancer, and melanoma models." (PMID 34885241, 2021).